SETD2 (SET domain containing 2, histone lysine methyltransferase)
Diseases named in the same sentence as SETD2 in open-access papers (continued):
Sharing a sentence is not in itself a finding about the gene and the disease.
prostate carcinoma (23 papers, 2020 to 2025). A carcinoma that arises from epithelial cells of the prostate gland. "SETD2 mutations have been identified in prostate cancer and it significantly clusters in prostate cancer samples over-expressing androgen receptors." (PMID 39591760, 2025). "In addition, analysis of mouse models and patient data showed that loss of SETD2 significantly promotes distant metastasis of prostate cancer." (PMID 37359376, 2023). "The results indicated that the SETD2 gene may be involved in the androgen receptor response pathway of prostate cancer, and that the SETD2 gene mutations have a potential role in the occurrence and development of castration-resistant prostate cancer (CRPC)." (PMID 37359376, 2023). "In the context of prostate cancer, SETD2 directly methylates enhancer of zeste homolog 2 (EZH2) at K735 to facilitate its degradation." (PMID 40746737, 2025). "SETD2 is an enzyme involved in transcription elongation and splicing and its expression was correlated with prostate cancer survival." (PMID 38983753, 2024). "SETD2 is a histone lysine methyltransferase playing a significant role in renal malignancies, prostate cancer, and NSCLC." (PMID 36653483, 2023). "Nevertheless, the potential roles of SETD2 in the diagnosis, treatment and prognosis of prostate cancer remain to be explored." (PMID 37359376, 2023). "Metformin hinders metastasis of prostate cancer cells by stimulating the expression of histone methyltransferase SETD2 (SET Domain Containing 2) while decreasing EZH2 (Enhancer of Zeste Homolog 2) and H3K27me3 levels." (PMID 36959680, 2023). "Recently, it was reported that SETD2 regulates the deposition of H3K36me3 by interacting with hnRNPL, and that SETD2 suppresses metastatic progression of prostate cancer by methylating EZH2 to lead its degradation." (PMID 35216000, 2022). "SETD2 can antagonize H3K27me3 effects in prostate cancer by adding methyl to EZH2 to facilitate its degradation." (PMID 34715919, 2021). "In the current study, we investigated the potential prognostic role of SETD2 in prostate cancer." (PMID 38611113, 2024). "Thus, we searched for germinal variants in ASXL1, CHD1, IDH1, SETD2 and TET2 epigenetic genes in Polish prostate cancer patients and controls and analyzed the impact of them on disease clinical course, including overall survival time." (PMID 39529133, 2024). "Our results showed that all cases of prostate cancer showed differentially expression of SETD2." (PMID 38611113, 2024). "Our data suggest a prognostic role for SETD2 in a prostate cancer cohort." (PMID 38611113, 2024). "It is worth nothing that investigations into the downstream signaling pathways of the SETD2 GSEA could elucidate critical molecular drivers of aggressive prostate cancer phenotypes." (PMID 38611113, 2024). "Additionally, four novel targets were predicted (IGF2R, C5AR/C5AR1, RAB7, and SETD2) which are all involved in molecular pathways closely connected to prostate cancer, with some having been recently proposed as suitable targets for other types of cancers." (PMID 38983753, 2024). "In this way, SETD2 antagonizes H3K27 methylation to suppress prostate cancer progression." (PMID 34715919, 2021). "Studies showed that SETD2/H3K36me3 expression was reduced in prostate cancer." (PMID 34715919, 2021). "Since EZH2 enables cells to acquire invasive traits, SETD2-mediated EZH2-K735me1 is functionally and clinically important to restrict prostate cancer metastasis." (PMID 40746737, 2025). "Using prostate cancer as a case study, the best features were identified and utilized to train machine learning algorithms to predict 5 novel promising therapeutic targets for prostate cancer: IGF2R, C5AR, RAB7, SETD2 and NPBWR1." (PMID 38983753, 2024).
prostate carcinoma (continued). "Metformin has been shown to combat EZH2-high prostate cancer by stimulating SETD2, which regulates EZH2-K735me1 to induce EZH2 destruction, thereby inhibiting prostate cancer metastasis." (PMID 37344841, 2023). "By connecting metabolic and epigenetic changes, SET domain-containing 2 (SETD2), a histone lysine methyltransferase, integrates enhancer of zeste homolog 2 (EZH2) and the AMPK signaling pathway to limit prostate cancer spread." (PMID 36831413, 2023). "The HPA database suggested that C18orf25, DYNC1LI2, SYNJ1, MAPK1, and ARID4B are highly expressed in normal tissues, and CLOCK, SETD2, ZNF654, XIAP, MIS18BP1, and MBTPS2 are highly expressed in prostate cancer tissues." (PMID 36249009, 2022). "SETD2, a histone methyltransferase and epigenetic modifier, and SETD2 protein expression were explored in a prostate cancer non-surgical cohort of 202 cases." (PMID 38611113, 2024). "SETD2 promotes the degradation of EZH2 by methylating the EZH2 K735 site, preventing transformation of cells to a high H3K27me3 chromatin state, thereby inhibiting the molecular mechanism of prostate cancer metastasis." (PMID 37359376, 2023). "Additionally, the GEPIA dataset indicated that SETD2 expression was positively correlated with FBW7 expression in ccRCC, prostate cancer, and bladder cancer." (PMID 35081978, 2022). "SETD2 (SET domain-containing 2, a histone lysine methyltransferase) integrates EZH2 (enhancer of zeste homolog 2) and the AMPK signaling pathway to restrict prostate cancer metastasis by linking metabolism with epigenetic modifications." (PMID 34050894, 2022). "SETD2-mediated mono-methylation of EZH2-K735 promotes EZH2 ubiquitination in prostate cancer." (PMID 33308321, 2020).
kidney cancer (18 papers, 2014 to 2024). Primary or metastatic malignant neoplasm involving the kidney. "A significant reduction in TMEM25 expression was observed among the mutation groups of BAP1, UNC80, EYS, SETD2 and XIRP, compared with the wild group, as BAP1 and SETD2 are commonly occurring mutation types in kidney cancer and have poor prognosis." (PMID 38189809, 2024). "SETD2 loss perturbs the kidney cancer epigenetic landscape to promote metastasis and engenders actionable dependencies on histone chaperone complexes." (PMID 37933774, 2023). "However, our results in both lung and kidney cancers show that loss of SETD2 counterintuitively increases oncogenic transcriptional output." (PMID 36810256, 2023). "Among the top 10 mutated genes found in the kidney cancer dataset, PBRM1, BAP1, SETD2, and VHL have been implicated in tumor progression and poor prognoses." (PMID 39199616, 2024). "According to the TCGA report, the most frequent gene mutations in kidney cancer were VHL, PBRM1, SETD2, and BAP1." (PMID 35055428, 2022). "In TCGA series, as in ours, SETD2 variation spanned melanoma and different kidney cancer subtypes, which is in line with the documented broad role of SETD2 in cancer." (PMID 34067022, 2021). "Collectively, our findings bring further argument for considering the SETD2 gene status of ccRCC tumors, when therapeutic interventions, such as targeting the autophagic process, are considered to combat these kidney cancers." (PMID 31988284, 2020). "Notably, for SETD2 and MECOM, mRNA levels were more than threefold and sixfold lower in kidney cancer cell lines, respectively." (PMID 30755832, 2019). "In both a distinct type of kidney cancer not characterized by chromosome 3p LOH or VHL inactivation, and a tumor of completely different cellular origin, we observed a DNA hypermethylation phenotype strongly linked to SETD2 mutation." (PMID 26646321, 2016).
pancreatic cancer (18 papers, 2020 to 2026). "A study on pancreatic cancer has shown that the loss of SETD2 can cause CAFs in the tumour to differentiate into a lipid‐rich phenotype." (PMID 41469334, 2026). "For example, SETD2 is suggested to be associated with a more aggressive tumor phenotype in GISTs and pancreatic cancer." (PMID 41228333, 2025). "SETD2 deficiency in pancreatic cancer thus reprograms glycolytic metabolism to compensate for insufficient nucleoside synthesis." (PMID 39591760, 2025). "Next, we aimed to elucidate mechanism by which SETD2 deficiency in pancreatic tumor reprogrammed neutrophils." (PMID 36453584, 2023). "The authors demonstrate that the tumor‐intrinsic Setd2 deficiency enhances recruitment and reprogramming of neutrophils in pancreatic tumor, thereby escaping from immune surveillance via inhibiting the cytotoxicity of CD8+ T cells." (PMID 36453584, 2023). "Here, it is shown that SETD2 deficiency can reprogram neutrophils to an immunosuppressive phenotype, thereby promoting immune escape during pancreatic tumor progression." (PMID 36453584, 2023). "More importantly, we further demonstrated the pro‐tumor function of infiltrating neutrophils in Setd2‐deficient pancreatic tumor progression." (PMID 36453584, 2023). "Collectively, Setd2 deficiency in pancreatic tumor cells not only enhances neutrophil chemotaxis but also rewires them into a pro‐tumoral phenotype with immunosuppressive cues." (PMID 36453584, 2023). "Setd2‐deficient pancreatic tumor cells directly enhance neutrophil recruitment and reprogramming, thereby inhibiting the cytotoxicity of CD8+ T cells to foster tumor progression." (PMID 36453584, 2023). "Our work provides mechanistic insights into how tumor‐intrinsic SETD2 deficiency reshapes the immunosuppressive TME via neutrophils, thereby providing the potential use of anti‐neutrophil immunotherapy in pancreatic cancer patients with SETD2 deficiency." (PMID 36453584, 2023). "The immunosuppressive microenvironmen in vivo ork, we found that neutrophils were major executors of immune escape in Setd2‐deficient pancreatic tumors." (PMID 36453584, 2023). "Taken together, we propose that tumor‐infiltrating neutrophils in Setd2‐deficient pancreatic tumors impair the cytotoxicity of CD8+ T cells, at least partially, in a PD‐L1/PD‐1 axis‐dependent manner." (PMID 36453584, 2023). "Here, our study reveals an anti‐neutrophil immunotherapy targeting pancreatic tumors with SETD2/H3K36me3 deficiency or low expression." (PMID 36453584, 2023). "Herein, above data imply that Setd2 deficiency enhances intratumoral neutrophil infiltration during pancreatic tumor progression." (PMID 36453584, 2023). "Herein, our results demonstrate that transcriptional repression in Setd2‐deficient pancreatic tumor cells is associated with both H3K36me3 loss and ectopic H3K27me3 deposition." (PMID 36453584, 2023). "SETD2 is a suppressor gene of K-Ras-associated pancreatic cancer, and its loss in acinar cells promotes K-RAS-induced pancreatic ductal reprogramming through epigenetic dysregulation of Fbxw7." (PMID 36741258, 2023). "By comprehensively comparing the intratumoral immune cell profiles between Setd2‐proficient and Setd2‐deficient groups, neutrophils were the subset with the most significant change in pancreatic tumors." (PMID 36453584, 2023). "SETD2 is downregulated in pancreatic cancer, and a low expression of SETD2 is linked to poor clinical prognosis." (PMID 36902253, 2023). "In pancreatic cancer, ablation of SETD2 caused the deletion of CTNNA1, thereby mediating the enhancement of EMT, which strongly suggests that CTNNA1 plays a role in suppressing EMT." (PMID 36741258, 2023). "Taken together, these data indicate that tumor‐infiltrating neutrophils are essential for Setd2‐deficient pancreatic tumor progression." (PMID 36453584, 2023).
pancreatic cancer (continued). "CTNNA1 inhibits tumor metastasis and cell growth through inhibition of EMT in bladder cancer, and the reversal of the oncogenic effect of EMT by miR-429 and Setd2 in colorectal and pancreatic cancers is also associated with CTNNA1." (PMID 36741258, 2023). "More interestingly, the lowest SETD2 expression is found in PanIN lesions, supporting that SETD2 is associated with the early development and metastasis in pancreatic cancer." (PMID 32231741, 2020). "SETD2 gene alters or mutates in around 10% patients with pancreatic cancer, and such data are consistent with TCGA 8,78." (PMID 32231741, 2020). "It is worth noting that the correlation between SETD2 loss and elevated neutrophils might be not only in pancreatic cancer but also in lung and colon cancers, which still needs further investigation." (PMID 36453584, 2023). "Another study published in Advanced Science in 2023 has indicated that tumor-intrinsic Setd2 deficiency enhances recruitment and reprogramming of neutrophils in pancreatic tumors, thereby escaping from immune surveillance via inhibiting the cytotoxicity of CD8+ T cells." (PMID 37184030, 2023). "The study provides mechanistic insights into how tumor cell‐intrinsic Setd2 deficiency strengthens the immune escape during pancreatic tumorigenesis, which may offer potential therapeutic implications for pancreatic cancer patients with SETD2 deficiency." (PMID 36453584, 2023). "Mechanistically, we revealed that SETD2‐H3K36me3 loss directly downregulated Cxadr expression in pancreatic tumor cells, allowing for PI3K‐AKT activation and the release of excessive CXCL1 and GM‐CSF, which attracted neutrophils and reprogrammed them toward an immunosuppressive phenotype." (PMID 36453584, 2023). "In addition, Cxadr overexpression largely rescued the excessive neutrophil infiltration and cytotoxic CD8+ T‐cell suppression in Setd2‐deficient pancreatic tumors." (PMID 36453584, 2023). "This work may provide an anti‐neutrophils strategy to potentiate the efficacy of immunotherapy in pancreatic cancer patients with SETD2 deficiency." (PMID 36453584, 2023). "In addition, SETD2 loss may be associated with pancreatic cancer because its loss leads to the ectopic expression of H3K27me3 and H3K27ac, which would contribute to the occurrence of immune escape in pancreatic ductal carcinoma 24-25." (PMID 40959108, 2025). "In pancreatic cancer, the expression of SETD2 is significantly decreased compared with normal tissues in around 10 % of the patients." (PMID 39591760, 2025). "According to transcriptome databases of human and murine pancreatic tumors, gene set enrichment analysis (GSEA) revealed that human pancreatic tumor with low level of SETD2 (TCGA‐PAAD) was coupled with enhanced inflammatory response." (PMID 36453584, 2023). "Herein, we highlight that tumor‐intrinsic SETD2 deficiency reshapes the immunosuppressive TME via neutrophils in pancreatic tumorigenesis, potentially providing a therapeutic strategy for pancreatic cancer patients with SETD2 deficiency." (PMID 36453584, 2023). "To explore how Setd2 loss leads to excessive neutrophil accumulation in the TME, we first compared the recruitment potential between Setd2KO and Setd2WT pancreatic tumor cells." (PMID 36453584, 2023). "The loss of SETD2 activates the BMP2 signaling pathway, driving CAFs to adopt a lipid‐rich phenotype that supports tumor cell growth through lipid transfer, thus promoting pancreatic cancer progression." (PMID 41164803, 2025). "However, in pancreatic cancer cells, Setd2 ablation results in sustained AKT activation through enhanced intrinsic extracellular matrix production, ultimately promoting tumor metastasis." (PMID 40554768, 2025). "One hypothesis about the role of SETD2 in the initiation and metastasis in pancreatic cancer would be on implication in cell metabolism." (PMID 39591760, 2025).
pancreatic cancer (continued). "Our previous study showed that the SETD2 expression level was closely related to H3K36me3 levels in pancreatic tumors.[8a] Here, we observed that the expression of SETD2/H3K36me3 was negatively correlated with MPO levels in pancreatic tumors (χ2 = 12.57, P < 0.001)." (PMID 36453584, 2023). "We found SETD2 overexpression was significantly higher in acute myeloid leukemia (AML), esophagus cancer, and pancreatic cancer compared to normal." (PMID 38611113, 2024).
colorectal cancer (14 papers, 2021 to 2026). A primary or metastatic malignant neoplasm that affects the colon or rectum. "Further analysis showed that a SETD2 deleterious mutation was an independent factor influencing MSI-H in colorectal carcinoma (P < 0.0001) and stomach adenocarcinoma (P = 0.003)." (PMID 37479966, 2023). "Furthermore, SETD2 associated in colorectal cancer with dMMRVAE1 at a FDR of 2%." (PMID 35764656, 2022). "Here the authors show that the histone H3K36 methyltransferase Setd2 is important for the survival of Treg cells and for the regulation of IL-33 mediated Th2 responses in mice and SETD2 expression is increased in Treg cells from human colorectal cancer tissue." (PMID 36463230, 2022). "Moreover, the authors observed elevated SETD2 expression in Tregs and reduced Th2 cells in cancerous tissues from colorectal cancer patients." (PMID 40746737, 2025). "The effect of Th2 cells in colorectal cancer is ambiguous; thus, elucidating the precise function of Th2 responses in colorectal cancer will facilitate the development and evaluation of novel cancer immunotherapeutics targeting SETD2 in Tregs." (PMID 40746737, 2025). "In colorectal cancer (CRC), the third most common and second most deadly cancer worldwide, SETD2 has also been shown to play a suppressive role." (PMID 39591760, 2025). "In colorectal cancer (CRC), SETD2 has been shown to regulate the Wnt signaling pathway in engineered mouse models (GEMs), and SETD2 loss promoted tumor progression." (PMID 37359376, 2023). "SETD2 sustains GATA3 expression in human Treg cells, and SETD2 expression is increased in Treg cells from human colorectal cancer tissues." (PMID 36463230, 2022). "In colorectal cancer, although SETD2 is not required for homeostasis in the intestine, SETD2 depletion results in tumorigenesis in the intestine of mice harboring heterozygous mutations in Apc, a tumor suppressor gene." (PMID 33923658, 2021). "Interestingly, we observed that increased SETD2 expression was accompanied by enhanced GATA3 expression in Treg cells in cancerous tissues from colorectal cancer (CRC) patients compared with noncancerous colorectal tissues." (PMID 36463230, 2022). "In colorectal cancer, further analysis revealed that TMB in non-MSI SETD2 mutant tumors (4.9, 2.8–132.2) was significantly higher than TMB in non-MSI SETD2 nonmutant tumors (2.5, 2.0–3.3; P < 0.0001)." (PMID 34127768, 2021).